DGAT1 (diacylglycerol O-acyltransferase 1)
Diseases named in the same sentence as DGAT1 in open-access papers (continued):
Sharing a sentence is not in itself a finding about the gene and the disease.
tumor (45 papers, 2014 to 2026). "GPX4-deficient tumor cells evade ferroptosis by upregulating the expression of DGAT1/2 to promote the synthesis of triacylglycerol (TAG) and oxidized TAG (oxTAG) and the formation of lipid droplets in cells." (PMID 41259048, 2026). "The upregulation of diglyceride acyltransferase 1(DGAT1), a key enzyme involved in exogenous fatty acid uptake and triglyceride synthesis, has been linked to tumor progression." (PMID 40696413, 2025). "A meta-analysis based on the TCGA database revealed that the overexpressed DGAT1 in GC tissues and tumor-infiltrating immune cells was associated with poor pathological differentiation and poor prognosis." (PMID 37206332, 2023). "Consistently, treatment with DGAT1/2 inhibitors or inducible overexpression of GPX4 in tumor cells significantly resensitizes tumor cells to ferroptosis and ignites the activation of T cells in the TME to inhibit NSCLC progression." (PMID 41259048, 2026). "Pharmacologic DGAT1 inhibition suppressed these pathways and elicited racially distinct regulation of tumor-promoting mediators, including BDNF, VEGF, and TSP1." (PMID 42118850, 2026). "Within tumor tissue, TG levels exhibited a positive correlation with DGAT1 at both the mRNA (r = 0.630, p = 0.008) and protein levels (r = 0.562, p = 0.026), while demonstrating a significant positive association with DGAT2 protein (r = 0.850, p = 0.003)." (PMID 41041279, 2025). "Both studies also point to mitochondria-related toxicity as a consequence of DGAT1 inhibition (DGATi) and the mechanism of DGATi-related tumor suppression." (PMID 40083687, 2025). "Significant correlation was observed between DGAT1 expression levels and tumor-infiltrating CD4+ T lymphocyte density." (PMID 40554491, 2025). "Inhibition of DGAT1 (diacylglycerol O-acyltransferase 1, an enzyme responsible for triacylglycerol synthesis) activity has also been found to cause excessive fatty acid oxidation, ROS generation and associated Nrf2 activation, which may inhibit tumor growth by inducing intolerable oxidative stress." (PMID 41197182, 2025). "In tumor tissue rich in the DGAT1 gene displayed raised survival was related with CD4 + T cells and dendritic cell." (PMID 40554491, 2025). "KU60019 treatment markedly impaired SKOV3 cell migration, an effect substantially reversed through DGAT1 inhibition, and the effect on tumor cells was greater than that on non-tumor cells." (PMID 40554491, 2025). "IC2 demonstrated a significant inhibition of tumor growth in the xenografted mice, and the addition of the DGAT1 inhibitor T863 further augmented the anti-tumor efficacy of IC2." (PMID 39725994, 2024). "In PC3-xenografted mice, the DGAT1 inhibitor augmented the IC2-induced reduction in tumor growth by modulating LD formation." (PMID 39725994, 2024). "Using the blastula transplant assay, we found a striking reduction in tumor growth in animals treated with a DGAT1 inhibitor." (PMID 37268606, 2023). "In glioblastoma xenografts, targeting DGAT1 disrupted lipid homeostasis, increased acylcarnitine accumulation, and induced oxidative stress, leading to suppressed tumor growth." (PMID 36776554, 2023). "Here, we show that targeting DGAT1 impairs lipid droplet biogenesis consequently leading to suppressed tumor growth and metabolic dysfunction." (PMID 37268606, 2023). "Our zebrafish and human models demonstrate that in melanocytes DGAT1 has the hallmarks of an oncoprotein, conferring a growth advantage especially under stress conditions likely encountered in the tumor microenvironment." (PMID 35732120, 2022). "Our recent study demonstrated that targeting DGAT1 to block TAG synthesis causes severe FA metabolism dysregulation in GBM cells, leading to mitochondria damage and ROS production that trigger tumor cell apoptosis." (PMID 36009491, 2022). "We show that inhibiting both DGAT1 and superoxide dismutase 1 profoundly suppress tumor growth through eliciting intolerable oxidative stress." (PMID 35732120, 2022).
tumor (continued). "Next, we explored the clinical relevance of DGAT1 and several key tumor-infiltrating immune cell subsets under a multivariable Cox proportional hazard model." (PMID 33750350, 2021). "Metabolic targeting has been proposed as a therapy for many tumor types, and inhibition of DGAT1 has recently been proposed to alter fat metabolism and increase oxidative stress in GBM." (PMID 34059134, 2021). "Important role of DGAT1 in energy metabolism indicated an active role of which in rapidly proliferating cells, such as tumor cells." (PMID 33750350, 2021). "Lipid droplets, MTOCs, and microtubule-regulating proteins were reduced in tumor cells treated with a DGAT1 inhibitor." (PMID 30816200, 2019). "In contrast, the DGAT1 inhibitor treated tumors had less tumor volume and a large area of necrosis (N) with karyorrhectic debris." (PMID 30816200, 2019). "GM130 was strongly positive in the cytoplasm of untreated tumor cells, while its expression was reduced in the tumors treated with a DGAT1 inhibitor." (PMID 30816200, 2019). "One DGAT1-related tumor suppressive mechanism involved GM130 since targeted knockdown of this protein induced less tumor proliferation and migration in vitro and revealed a feedback loop linking ncMTOCs and lipogenesis." (PMID 30816200, 2019). "It seems that the regulatory effect of DGAT1 on tumor progression involves many aspects." (PMID 40554491, 2025). "Notably, DGAT1 inhibition significantly impairs tumor growth in melanoma-B16F10 and Lewis lung carcinam-LLC models in C57/BL6 mice, highlighting its potential as a therapeutic target warranting further investigation." (PMID 40696413, 2025). "Furthermore, a significant association was found between elevated levels of DGAT1, DGAT2, PLIN2, PLIN3, and TG and malignancy, especially in advanced tumor stages, underscoring their promise as therapeutic targets in OC." (PMID 41041279, 2025). "The inhibition of DGAT1/2 restored the killing effect of HDNs on tumor cells." (PMID 41214328, 2025). "This suggests that tissue DGAT1 may play a role in regulating TG secretion into the PF, and the levels of TG in the PF could potentially reflect tissue DGAT1 levels and tumor aggressiveness." (PMID 41041279, 2025). "The culture conditions without glucose reduced the ability of teHDNs to store obtained lipids in LDs; decreased their proliferation, DGAT1 expression, and mTOR phosphorylation levels; and decreased their survival ability and ability to promote tumor cell proliferation." (PMID 41214328, 2025). "Targeting DGAT1 is an effective strategy for tumor treatment." (PMID 40554491, 2025). "The influence of DGAT1 on anti-tumor therapy is currently under investigation." (PMID 40554491, 2025). "Finally, in a human tumor xenograft model, a PUFA-rich diet delayed tumor growth in a ferroptosis-dependent manner, and combining a PUFA-rich diet with DGAT1 inhibitor treatment further suppressed tumor progression." (PMID 36776554, 2023). "In addition, our study showed that the DGAT1 inhibitor A922500 dramatically suppresses GBM tumor growth in a subcutaneous mouse model." (PMID 36009491, 2022). "We wished to establish whether pharmacological inhibition of DGAT1 would be a viable strategy to halt tumor growth in mice." (PMID 35732120, 2022). "The treatment with a DGAT1 inhibitor reduced the tumor volume nearly 84% (DGAT1 in." (PMID 30816200, 2019). "Moreover, higher levels of DGAT1 in more aggressive tumors would sustain growth and migration, whereas, blockade of DGAT1 would facilitate tumor suppressive activity." (PMID 30816200, 2019). "This association may not be perceived that IC2 exerted anti-tumor effects through LD formation, as reducing LD formation by a DGAT1 or ACC inhibitor actually enhanced the anti-tumor effects of IC2." (PMID 39725994, 2024). "Next, we wonder if block DGAT1 could inhibit tumor cell growth and metabolism." (PMID 33750350, 2021).
tumor (continued). "Remarkably, A922500 treatment in the presence of sodium oleate induced cell apoptosis and necrosis, which again proved that high level of DGAT1 might facilitate the tumor growth and inhibition of increased DGAT1 expression effectively suppressed cell expansion in vitro." (PMID 33750350, 2021). "Thus, therapeutic targeting of DGAT1 potentially has tumor suppressive activity." (PMID 30816200, 2019). "The addition of the mTOR inhibitor rapamycin reduced IL33-induced LD formation and DGAT1/2 and PPARG expression, as well as the survival ability, proliferation ability, and ability to promote tumor cell proliferation of teHDNs." (PMID 41214328, 2025). "The presence of LDs compromises the anti-tumor effects of IC2, highlighting the strategy of combining IC2 with a DGAT1 inhibitor to enhance its effectiveness." (PMID 39725994, 2024). "Several inhibitors of DGAT1 and DGAT2 have been created over the past decade, showing anti-tumor effects in pre-clinical models of tumors and metabolic improvements in clinical trials." (PMID 38500157, 2024). "By reprogramming the activities of DGAT1 and DGAT2, tumor cells can form more LDs to tolerate their enhanced free FA metabolism and prevent possible lipotoxicity and cell death." (PMID 38500157, 2024). "Strikingly, combined DGAT1 and SOD1 inhibition led to a profound reduction in tumor growth, with most animals demonstrating tumor regression in the MM485 xenograft model." (PMID 35732120, 2022). "We next assessed the impact of combining inhibition of DGAT1 and SOD1 on tumor growth by using not only the BRAFV600E-mutant A375 xenograft model but also an NRASQ61R-mutant MM485 xenograft model." (PMID 35732120, 2022). "We discovered that blockade of DGAT1 not only reduced LD density and PLIN2, but it also had potent anti-tumor activities by suppressing tumor growth both in vitro and in vivo." (PMID 30816200, 2019). "Additionally, DGAT1 and DGAT2 play crucial roles in tumor dynamics by modulating epithelial‐mesenchymal transition (EMT), influencing both tumor invasion and metastasis." (PMID 41041279, 2025). "The phenomenon we observed was different from the findings of previous reports that tumor cells rely solely on DGAT1 rather than DGAT2 to regulate TG synthesis and LD formation." (PMID 41214328, 2025). "Notably, we found significant correlations between DGAT1 and DGAT2 mRNA expression and the tumor aggressiveness marker Ki67." (PMID 41041279, 2025). "Conversely, several genes, such as ZMAT3 and DGAT1, demonstrated reduced or absent staining in tumor tissues relative to normal tissues, indicating potential tumor-suppressive functions." (PMID 40299459, 2025). "Similarly, FABP7 can be upregulated by HIF-1α to enhance DGAT1 activity in macrophages, which in turn delivers lipids to CD8+ T-cells and tumor cells via exosomes, resulting in CD8+ T-cell dysfunction and tumor cell proliferation." (PMID 41226585, 2025). "Notably, different roles of DGAT1 and DGAT2 in tumor growth and prognosis have been reported in different types of tumors, increasing the difficulty of applications of DGATs in the clinical setting." (PMID 38500157, 2024). "To demonstrate the interaction between DGAT1 and SOD1 on tumor growth in vivo, we have again relied on pharmacological agents that may have generated off-target effects that contributed to tumor growth inhibition." (PMID 35732120, 2022). "However, simultaneous DGAT1 and SOD1 inhibition leads to catastrophic levels of ROS accumulating in tumor cells, triggering their death." (PMID 35732120, 2022). "According to the changes of the expression status of differential molecules between the two networks, we identified the top 10 differential mRNAs (PRKAA2, NLGN4X, ST6GALNAC3, DGAT1, TRIB1, GRPR, and MLLT11) and lncRNAs (n339695, n378130, and n410438) in the tumor–endothelium interaction." (PMID 33681194, 2021).
tumor (continued). "Inhibition of DGAT1 reduced tumor growth both in vitro and in vivo, and a negative feedback loop was discovered between DGAT1, PEDF, and GM130." (PMID 30816200, 2019). "Interestingly, the increased protein levels in tumor tissues compared with nonmalignant tissues was more pronounced for DGAT1 than for DGAT2, despite DGAT2′s higher baseline levels." (PMID 41041279, 2025). "Similarly, IL33 impaired the killing ability of HDNs against tumor cells, an effect that was rescued by DGAT1/2 inhibition; CSF2 did not impair the killing ability of HDNs against tumor cells." (PMID 41214328, 2025). "KRAS-Mut tumors showed significant upregulation of tumor migration (TGFBR2-S553 and EPHB3) and PI3K/AKT activation (PIP4K2C and PIK3R1), while the KRAS-WT group was enriched in immune regulation (TAP1/2, IFITM1, and IFIH1-S301) and cellular metabolism (DGAT1 and HINT3)." (PMID 35836817, 2022). "Since inhibition of DGAT1 was able to reduce tumor cell proliferation and migration, we investigated whether GM130 could be one potential molecular mechanism responsible for anti-tumor activity of a DGAT1 inhibitor." (PMID 30816200, 2019). "Also in this case, the pharmacological inhibition of ACAT1 (but not DGAT1) alleviated tumor growth." (PMID 40083687, 2025). "Thus the inhibition of the intestinal DGAT1 may be sufficient to improve metabolic disorders, suggesting that the intestine-targeted DGAT1 inhibitor shows beneficial metabolic effects without skin aberrations." (PMID 25405858, 2014). "We found that DGAT1 is overexpressed in tumor tissues from GBM patients and genetic or pharmacological inhibition of DGAT1, but not DGAT2, suppresses LD/TAG formation and reduces GBM tumor growth." (PMID 36009491, 2022). "In both models, similarly to DGAT1 inhibition alone, SOD1 inhibitor treatment alone had no significant impact on tumor growth." (PMID 35732120, 2022).
infection (21 papers, 2017 to 2025). The state of being infected such as from the introduction of a foreign agent such as serum, vaccine, antigenic substance or organism. "Reduced T. cruzi amastigote proliferation in DGAT1/2-deficient fibroblasts further underscored the importance of parasite coupling to host triacylglycerol pools during the intracellular infection cycle." (PMID 29281741, 2017). "Progeny from both parent plants inherited DGAT + CO at approximately 1:1 with 100% endophyte infection observed in seed collected from the E + parent based upon analysis by PCR, immunoblotting for DGAT1 and the presence of the endophyte." (PMID 38072924, 2023). "The DGAT1 protein levels were decreased at day 4 and day 6 post-infection in HCV J6/JFH1-infected cells (lanes 4 and 6)." (PMID 40396035, 2022). "Here, we identified diacylglycerol O-acyltransferase 1 (DGAT1) to be essential for accumulation of triglyceride in necrotic TB granulomas using the C3HeB/FeJ murine model of infection." (PMID 34603294, 2021). "In this study we found that DGAT1 inhibition can lead to better control of bacterial growth in vivo, via reducing the detrimental inflammatory immune response to infection." (PMID 34603294, 2021). "As Dgat1 expression induced by d14, we further tested impact of treatment starting at d7 post infection." (PMID 34603294, 2021). "Together, the intravenous dosing of T863 in a high dose model revealed DGAT1 activity to be essential for granuloma TG synthesis and was a suitable methodology to test the role of DGAT1 activity in infection progression." (PMID 34603294, 2021). "Here, we demonstrate that DGAT1 is not only induced upon infection, but is also essential for TG accumulation in the granuloma." (PMID 34603294, 2021). "For these experiments, we pre-treated the VERO cells with a range of concentrations of DGAT-1 inhibitor A922500 (0.1–50 μM) for 2 hours, followed by infection with SARS-CoV-2 (MOI 0.01) for 24 hours in the presence of the inhibitor." (PMID 33326472, 2020). "Infection induced release of all of these cytokines decreased upon depletion of DGAT1 transcripts in macrophages despite their prior stimulation with NcS, confirming the role of TGs in the inflammatory response to infection." (PMID 30018616, 2018). "The increased TG levels in necrosis-associated foamy macrophages promoted the pro-inflammatory state of macrophages to infection while silencing expression of diacylglycerol O-acyltransferase (DGAT1) suppressed expression of pro-inflammatory genes." (PMID 30018616, 2018). "DGAT1 knockdown led to approximately 50% decrease in infection induced TNFα in the supernatant in case of NM." (PMID 30018616, 2018). "Treatment of M. tuberculosis infected, IFN-γ activated BMDM with the DGAT1 inhibitor T863 prevented LD formation during the first 24 hours after infection and this defect in LD formation continued through 3 days after infection." (PMID 29370315, 2018). "These lipid-laden foamy macrophages mount a heightened inflammatory response to infection which can be suppressed by targeting diacylglycerol O-acyltransferase (DGAT1)." (PMID 30018616, 2018). "In addition, HCV J6/JFH1 infection leads to DGAT1 degradation, which is inhibited by ammonia chloride, suggesting that DGAT1 is a substrate of lysosomal degradation." (PMID 39599533, 2024). "The induction of Dgat1 as early as d14 post infection led us to question whether DGAT1 activity in the granuloma affects the sustained inflammatory response to infection." (PMID 34603294, 2021). "We observed 2.5-fold induction of Dgat1 by d14 post infection." (PMID 34603294, 2021). "SARS-CoV-2 infection of human primary monocytes up-regulated the pathways involved in lipid uptake such as CD36, the major transcriptional factors involved in lipogenesis, PPARγ and SREBP-1, and the enzyme DGAT-1, which is involved in triacylglycerol synthesis, after 24 hours of infection." (PMID 33326472, 2020).
infection (continued). "To further test if cytokine production in response to infection was proportional to intracellular TG levels, we differentiated DGAT1 shRNA and control shRNA expressing THP1 cells with NcS and then sought to measure release and expression of TNFα in response to Mtb infection." (PMID 30018616, 2018). "Similarly, DGAT1 inhibition in primary human macrophages prevented LD formation during the first 24 hours after infection." (PMID 29370315, 2018). "Besides, PPARγ, some of the critical enzymes involved in fatty acid biosynthesis, TAG biosynthesis, cholesterol esterification like Fasn, Dgat1, Dgat2, Mgat1, Acat1, Acat2, etc., showed a temporal increase in expression levels at the later time points post-infection." (PMID 41358489, 2025). "In contrast, DGAT1 and DGAT2 mRNA levels remained relatively stable, with DGAT2 mRNA levels significantly decreasing at 48 hours post infection." (PMID 41306517, 2025). "We treated newborn (P2) to P9 mice with an intraperitoneal injection of the A922500 DGAT-1 inhibitor daily and infected them afterwards with a dose of 2 × 107 PFU of Brazilian ZIKV strain to induce an acute infection according to previous studies." (PMID 36882750, 2023). "Pharmacological inhibition of DGAT-1 decreased LD accumulation and ZIKV replication in vitro in human cells and in an in vivo mouse model of infection." (PMID 36882750, 2023). "Interestingly, in this study, DGAT1 and DGAT2 knockdown in human colonic Caco-2 cells and lung Calu-3 cells led to significantly reduced viral yields following infection compared to control-transfected cells." (PMID 37113005, 2023). "Monoacylglycerol acyltransferases (MOGATs), lipin phosphatidic acid phosphatases (LIPINs), and diacylglycerol acyltransferases (DGATs) are key enzymes in TAG biosynthesis, and all the three types of enzymes were downregulated upon infection, including MOGAT1/2/3, LPIN3, and DGAT1/2." (PMID 33314005, 2021). "The localization of Dgat1-GFP did not change during infection, remaining at the ER at all stages." (PMID 28103313, 2017). "In this context, it is interesting that the intracellular growth of M. marinum as measured by bacterial luciferase activity was not different in wild type cells and Dgat1- or Dgat2-GFP overexpressors, even when fed with FA prior to infection." (PMID 28103313, 2017).